CYB561 (cytochrome b561)
Description:
Transmembrane reductase that probably uses ascorbate as an electron donor to reduce Fe(3+) into Fe(2+) and could play a role in iron transport. It is also able to reduce extracellular monodehydro-L-ascorbate and could be involved in the regeneration and homeostasis within secretory vesicles of ascorbate which in turn provides reducing equivalents needed to support the activity of intravesicular enzymes.
Synonyms: FRRS2; CYB561A1; CGCytb; ORTHYP2
Tractability: Antibody: UniProt predicts a signal peptide or a membrane-spanning region. PROTAC: ubiquitination databases record sites on it.
Gene: Protein-coding gene on chromosome 17 (63,432,298 to 63,447,108, reverse strand). Ensembl gene ENSG00000008283.
Subcellular location: Cytoplasmic vesicle, secretory vesicle, chromaffin granule membrane
Gene Ontology:
Molecular function: protein binding; transmembrane ascorbate ferrireductase activity; transmembrane monodehydroascorbate reductase activity; oxidoreductase activity
Biological process: ascorbate homeostasis; electron transport chain; intracellular iron ion homeostasis; transmembrane transport
Cellular component: chromaffin granule membrane; membrane
Genetic constraint (gnomAD): Loss-of-function variants: 11 observed, 25.75 expected, observed/expected ratio (o/e) 0.43, 90% interval 0.27 to 0.71. The upper end of that interval is the gene's LOEUF score, 0.71, which puts it in group 2 of 6, group 1 being the genes least tolerant of losing a copy. Missense variants: 295 observed, 342.21 expected, observed/expected ratio (o/e) 0.86, 90% interval 0.78 to 0.95. Synonymous variants: 165 observed, 163.84 expected, observed/expected ratio (o/e) 1.01, 90% interval 0.89 to 1.15.
Homologues: Orthologues: chimpanzee CYB561 (99% identical), guinea pig CYB561 (88% identical), mouse Cyb561 (88% identical), rat Cyb561 (87% identical), rabbit CYB561 (86% identical), pig CYB561 (85% identical), macaque CYB561 (81% identical), dog CYB561 (75% identical), zebrafish cyb561 (59% identical), tropical clawed frog cyb561 (58% identical), Caenorhabditis elegans F55H2.5 (35% identical), Drosophila melanogaster nemy (28% identical), and 2 more. Paralogues in human: CYBRD1 (39% identical), CYB561A3 (39% identical).
Diseases named in the same sentence as CYB561 in open-access papers:
CYB561 is named in the same sentence as 23 diseases in open-access papers, as found by Europe PMC text mining. Sharing a sentence is not in itself a finding about the gene and the disease. The quoted sentences say what the papers report.
breast carcinoma (6 papers, 2022 to 2026). "Our findings establish CYB561 as a master regulator of BC progression and nominate it as a promising therapeutic target for aggressive breast cancers." (PMID 41974658, 2026). "Studies reported that CYB561 is highly expressed in tissues of breast cancer patients and correlates with poor prognosis, and low expressed in endometrial cancer and ovarian cancer, also correlating with poor prognosis." (PMID 38245506, 2024). "In 2022, bioinformatic analysis has reported that CYB561 expression and clinical prognostic value in breast cancer." (PMID 38245506, 2024). "Our analysis also identified a breast cancer–specific AF event involving two isoforms of CYB561, including a novel isoform identified by LR-seq." (PMID 35044822, 2022). "CYB561 is an electron carrier enzyme that was recently identified as a novel prognostic factor in breast cancer." (PMID 35044822, 2022). "CYB561 serves as a potential prognostic biomarker and target for breast cancer." (PMID 35836577, 2022). "In the present study, our data analysis demonstrated that CYB561 expression was higher in breast cancer than in non-tumor tissues, high expression of CYB561 is associated with a shorter survival period in patients with BRCA." (PMID 38245506, 2024).
prostate carcinoma (2 papers, 2024). A carcinoma that arises from epithelial cells of the prostate gland. "Studies have identified CYB561 as a therapeutic target and biomarker in neuroendocrine prostate cancer cells, and highlight the potential use of that can be used to identify more aggressive disease." (PMID 38245506, 2024).
amyotrophic lateral sclerosis (1 paper, 2025). Amyotrophic lateral sclerosis (ALS) is a neurodegenerative disease characterized by progressive muscular paralysis reflecting degeneration of motor neurons in the primary motor cortex, corticospinal tracts, brainstem and spinal cord. "In our AD EA TWAS, we also identified genes associated with other neurological and autoimmune diseases, including Parkinson’s disease (CYB561 and SLC25A39), Crohn’s disease (ATG16L1), Amyotrophic lateral sclerosis (SIGLEC9), and Riboflavin Transport Deficiency (SLC52A1)." (PMID 40141087, 2025).
endometrial carcinoma (1 paper, 2022). A malignant tumor arising from the epithelium that lines the cavity of the uterine body. "How the AP contributes the low expression of CYB561 in endometrial carcinoma remains to be further explored." (PMID 35836577, 2022).
Infertility (1 paper, 2023). "Other genes are related to symptoms that are still under investigation, such as neurological sequels (CYB561 and LCMT2) and infertility (RPSAP58 and ASRGL1)." (PMID 36674947, 2023).
lobular carcinomas (1 paper, 2024). "The results of the Human Protein Atlas (HPA) database analysis showed that certain ductal and lobular carcinomas had elevated levels of CYB561 expression compared to normal tissues." (PMID 38245506, 2024).
lung carcinoma (1 paper, 2022). "We subsequently performed transwell assays to determine the effects of lnc‐CYB561‐5 on the migration and invasion of H1299, H292 and A549 cells, and the results showed that a low level of lnc‐CYB561‐5 was closely associated with the invasion ability of lung cancer cell." (PMID 35064752, 2022). "Further studies suggested that the high expression of lnc‐CYB561‐5 in lung cancer cells significantly promotes cell proliferation, migration and invasion in vitro and in vivo." (PMID 35064752, 2022). "Therefore, the involvement of lnc‐CYB561‐5 in the regulation of lung cancer cell metabolism, proliferation and metastasis is Bsg dependent." (PMID 35064752, 2022).
ovarian carcinoma (1 paper, 2022). A malignant neoplasm originating from the surface ovarian epithelium. "A meta-analysis showed that low mRNA expression of CYB561 was prognostic of a poor outcome in ovarian cancer." (PMID 35836577, 2022).
prostate tumor (1 paper, 2024). "From our in silico analysis, we found that CYB561 mRNA is upregulated in several cancer types, with the highest expression levels observed in prostate tumor samples." (PMID 38739593, 2024).
cancer (6 papers, 2014 to 2024). A tumor composed of atypical neoplastic, often pleomorphic cells that invade other tissues. "CYB561 is involved in the α-amidation-dependent activation of neuropeptides, and contributes to regulating iron metabolism which is often dysregulated in cancer." (PMID 38739593, 2024). "CYB561 also influences intracellular iron metabolism, another dysregulated pathway in various cancer types." (PMID 38739593, 2024). "To ascertain if the effects of CYB561 knockdown on NE phenotype and iron metabolism would translate to changes in the highly aggressive nature of PC-3 cells, we evaluated the consequences of CYB561 knockdown on several hallmarks of cancer cell behavior." (PMID 38739593, 2024). "To filtrate CYB561 promoting cancer mechanisms, we investigated the protein level of H2AFY and NF-κB in subcutaneous tumors." (PMID 38245506, 2024). "In further dissecting the cancer-promoting mechanisms of CYB561 and identifying the potential substrates of CYB561, we overexpressed CYB561 in HEK293T cells, HEK 293T cells that were transfected with an empty vector were shown as a control." (PMID 38245506, 2024). "By integrating these two pathways, CYB561 sustains the NE phenotype and promotes a more aggressive cancer cell behavior by supporting cell survival, proliferation, and migration in vitro." (PMID 38739593, 2024). "In NEPC PC-3 cells, depletion of CYB561 reduced the secretion of growth-promoting factors, lowered intracellular ferrous iron concentration, and mitigated the highly aggressive nature of these cells in complementary assays for cancer hallmarks." (PMID 38739593, 2024). "However, no experimental studies or clinical data have shown that lnc‐CYB561‐5 is an important regulator or biomarker of cancer progression." (PMID 35064752, 2022). "However, data on the role of the CYB561 gene in human cancers are very limited." (PMID 35836577, 2022). "While assessing the relationship between SLC31A1 and these genes, we discovered that CYB561, URF4, and EML5 were significantly correlated with SLC31A1 expression in the preponderance of cancers." (PMID 37853210, 2023). "Our list of genes overexpressed in cancer is also enriched in certain antioxidant enzymes (peroxiredoxins 1 and 3 (PRXD1 and PRXD3) and cytochrome b561 (CYB561))." (PMID 25243088, 2014). "In this study, we identified a novel lncRNA, namely lnc‐CYB561‐5 (Gene ID: ENSG00000233635), which is markedly upregulated in malignant lung cancer and potentially correlated with the prognosis of NSCLC patients in The Cancer Genone Atlas (TCGA) database." (PMID 35064752, 2022). "Knocking down CYB561 in the NEPC cell model PC-3 decreased the expression of NED markers and secretion of growth-promoting factors, lowered the intracellular Fe2+concentration, affected IRG expression, and reduced overall aggressive cancer cell behavior based on several cancer hallmarks." (PMID 38739593, 2024).
tumor (6 papers, 2021 to 2024). "Six out of 13 dysregulated genes in the TH group were associated with Treg fractions, but only CYB561 showed a positive correlation with the level of Tregs and tumor relapse (left, and d)." (PMID 33772139, 2021). "The pattern of increasing CYB561 amplification as the tumor progresses to CRPC and NEPC was also observed for PAM and genes encoding neuropeptide receptors further associating therapy resistance with the activation of neuropeptide signaling genes." (PMID 38739593, 2024). "The complex effects triggered by mere manipulation of CYB561 expression level in PCa cell models suggest that CYB561 has a significant contribution in facilitating PCa tumor behavior." (PMID 38739593, 2024). "Since CYB561 is involved in paracrine signaling through its function in neuropeptide activation, we investigated the consequences of CYB561 knockdown on the secretion of paracrine factors that may support tumor growth." (PMID 38739593, 2024). "Correlation analysis demonstrated that high levels of lnc‐CYB561‐5 were associated with tumour stage (p < 0.05) and lymph node metastasis (p < 0.05)." (PMID 35064752, 2022). "In vivo, downregulation of lnc‐CYB561‐5 significantly decreases tumour growth and metastasis." (PMID 35064752, 2022). "Interestingly, experimental demonstration that CYB561 can regulate H2AFY expression at the protein level and enhanced H2AFY protein stability, facilitated H2AFY nuclear expression, therefore fostering ectopic subcutaneous tumor proliferation." (PMID 38245506, 2024).
CYB561 also shares sentences with these, for which no sentence is quoted: acute myeloid leukaemia (1 paper); autoimmune disease (1); bladder urothelial carcinoma (1); breast invasive carcinoma (1); cholangiocarcinoma (1); colorectal cancer (1); Crohn disease (1); leukemia (1); metastatic disease (1); orthostatic hypotension (1); Parkinson disease (1); stomach adenocarcinoma (1).